SPRY1 (sprouty RTK signaling antagonist 1)
Diseases named in the same sentence as SPRY1 in open-access papers (continued):
Sharing a sentence is not in itself a finding about the gene and the disease.
psoriasis (3 papers, 2022 to 2025). An autoimmune condition characterized by red, well-delineated plaques with silvery scales that are usually on the extensor surfaces and scalp. "Based on our previous findings that Spry1 in keratinocytes suppresses psoriasis-like skin inflammation by inhibiting cathelicidin production and cutaneous immune activation, we next examined the impact of Spry1 loss in epidermal keratinocytes." (PMID 40694426, 2025). "Epidermis-specific SPRY1-deficient mice spontaneously develop psoriasis-like skin lesions and arthritis." (PMID 40471688, 2025). "This keratinocyte SPRY1/CXCL10/periarticular CD14hi macrophage/TNF-α axis provides valuable insights into the mechanisms underlying the transition from psoriasis to PsA and suggests potential therapeutic targets for preventing this progression." (PMID 40471688, 2025). "In this study, we generated epidermis-specific SPRY1-deficient (Spry1-cKO) mice and, surprisingly, observed that these mice spontaneously developed psoriasis-like skin inflammation and arthritis, closely resembling PsA." (PMID 40471688, 2025). "The dysregulation of DGAT2 and lipid metabolism enhances TLR3-mediated inflammation in keratinocytes and promotes CD8+ T cell activation, driving psoriasis development in keratinocyte-specific SPRY1-deficient mice." (PMID 40694426, 2025). "Here, we generated epidermis-specific SPRY1-deficient (Spry1-cKO) mice and, surprisingly, observed that these mice spontaneously developed psoriasis-like skin lesions and arthritis." (PMID 40471688, 2025). "To gain a better understanding of how epidermal SPRY1 negatively regulates the development of psoriasis, we generated K14CreERTSpry1fl/fl mice by crossing mice with loxP-flanked Spry1 alleles (Spry1fl/fl) with keratin 14-Cre/ERT (K14-CreERT) transgenic mice." (PMID 40471688, 2025). "Collectively, these phenotypical, histological, immunological, and molecular changes observed in the skin and joints of Spry1-cKO mice exhibited hallmarks of psoriasis and PsA." (PMID 40471688, 2025). "Our previous studies have shown that SPRY1 possesses antiinflammatory properties and plays a protective role in psoriasis by regulating cutaneous innate immune responses." (PMID 40694426, 2025). "Six weeks after the first tamoxifen induction, almost 100% of Spry1-cKO mice developed arthritis in paws (dactylitis) and psoriasis-like skin inflammation on their ears and paws, while 70% of Spry1-cKO mice showed psoriasis-like dermatitis on the back." (PMID 40471688, 2025). "In this study, we generated a keratinocyte-specific Sprouty RTK signaling antagonist 1 (SPRY1) knockout (Spry1ΔEpi) mouse model, which exhibits psoriasis-like symptoms." (PMID 40694426, 2025). "To investigate its role further, we generated a keratinocyte-specific Spry1-knockout (Spry1ΔEpi) mouse model, which exhibited psoriasis-like features, including scaling, skin thickening, and hyperpigmentation." (PMID 40694426, 2025). "Since SPRY1 plays a protective role in IMQ‐induced psoriasis‐like skin inflammation, we investigated how SPRY1 regulated skin inflammation in human epidermal keratinocytes." (PMID 35716036, 2022). "Additionally, overexpression of SPRY1 in mice ameliorated imiquimod-induced psoriasis-like skin inflammation." (PMID 40471688, 2025). "Interestingly, 3 weeks after the first tamoxifen induction, some Spry1-cKO mice developed diffuse erythematous and scaly plaques on the back and ears (closely resembling the skin lesions of human psoriasis)." (PMID 40471688, 2025). "Moreover, Gene Set Enrichment Analysis (GSEA) showed significant overlap in the transcriptional signatures of skin lesions between Spry1-cKO mice (epidermis plus dermis) and 58 patients with psoriasis (GEO GSE13355)." (PMID 40471688, 2025). "Accordingly, epidermal SPRY1 may be an early indicator of psoriatic inflammation, which may be involved in the pathogenesis of psoriasis initiation, recovery and relapse." (PMID 35716036, 2022).
psoriasis (continued). "Together, epidermal SPRY1 was dynamically expressed during psoriasis initiation, recovery and relapse, which may be involved in psoriasis pathogenesis." (PMID 35716036, 2022). "Therefore, IMQ was used to assess the role of SPRY1 in the development of psoriasis." (PMID 35716036, 2022). "In vivo, utilizing epidermis‐specific Krt14‐SPRY1 transgenic mice, LL37 decreased significantly when Spry1 epidermis‐specific overexpressed, in a psoriasis‐like mouse model." (PMID 35716036, 2022). "The observed positive correlation between SPRY1 and DGAT2 mRNA levels in psoriasis datasets may reflect a shared upstream regulatory mechanism, which needs further investigation." (PMID 40694426, 2025). "Immunohistochemical staining and immunofluorescence were used to detect Sprouty1 (SPRY1) expression in human psoriatic skin with and without anti‐psoriasis treatments." (PMID 35716036, 2022). "Therefore, based on the results of Krt14‐SPRY1‐tg mice, which exhibited less level of cathelicidin in the epidermis than WT mice, we may conclude that SPRY1 and LL37 are negatively and mutually regulated in psoriasis." (PMID 35716036, 2022).
acute myeloid leukemia (2 papers, 2022). Acute myeloid leukemia (AML) is a group of neoplasms arising from precursor cells committed to the myeloid cell-line differentiation. "SPRY1 was remarkably overexpressed in acute myeloid leukemia (AML) patients-derived cells and contributed to cell cycle progression and cell proliferation, suppressing cell apoptosis by activating the Hedgehog pathway." (PMID 35910677, 2022).
atrial fibrillation (2 papers, 2020). A disorder characterized by an electrocardiographic finding of a supraventricular arrhythmia characterized by the replacement of consistent P waves by rapid oscillations or fibrillatory waves that vary in size, shape and timing and are accompanied by an irregular ventricular response. "Very similar results confirming the pro-fibrotic role of miR-21 in atrial fibrillation via targeting Spry1 have been obtained in a rat experimental model of AMI." (PMID 31973111, 2020). "The important role of miR-21 in the pathogenesis of cardiac fibrosis has been shown also in heart atria from patients with atrial fibrillation likely via targeting its downstream target Sprouty 1 (Spry1)." (PMID 31973111, 2020). "Upregulated miR-21 in the left atria leads to the downregulation of its downstream molecule SPRY1 in atrial fibrillation (AF) patients." (PMID 33329700, 2020).
craniosynostosis (2 papers, 2016 to 2023). Craniosynostosis is defined as the premature fusion of one or more cranial sutures leading to secondary distortion of skull shape resulting in skull deformities with a variable presentation. "Here, we describe a homozygous SPRY1 nonsense variant, identified in a patient with syndromic craniosynostosis." (PMID 36543535, 2023). "Analysis of whole-genome sequencing data from individuals with craniosynostosis enrolled in the 100,000 Genomes Project identified a likely pathogenic variant within SPRY1." (PMID 36543535, 2023). "Moreover, in mice with TWIST1 haploinsufficiency, a model of syndromic craniosynostosis, overexpression of SPRY1 prevents suture fusion." (PMID 27606499, 2016).
esophageal cancer (2 papers, 2022 to 2024). A primary or metastatic malignant neoplasm involving the esophagus. "FGF2 as an important regulator of SPRY1 expression was involved in establishing the dysfunctional state of CD8+ T cells in esophageal cancer." (PMID 35785171, 2022). "Previous studies have reported a pro-Tex role for CBL in diseases such as esophageal cancer, in which CBL interacts with SPRY1 to promote Tex, contributing a pro-cancer effect." (PMID 39239096, 2024).
Ewing sarcoma (2 papers, 2013 to 2021). A small round cell tumor that lacks morphologic, immunohistochemical, and electron microscopic evidence of neuroectodermal differentiation. "We have shown that the re-expression of the BCL11B repressed gene, SPRY1, reduces the transformation potential of Ewing sarcoma cells." (PMID 23527175, 2013). "We tested this by expressing a 3xFLAG-tagged SPRY1 cDNA in the A673 Ewing sarcoma cell line and performing growth curves and in vitro transformation assays." (PMID 23527175, 2013). "In contrast to these studies, Spry1 fulfills the criteria of a tumor suppressor in Ewing’s sarcoma." (PMID 34769378, 2021). "Because RAS/MAPK signaling contributes to cell growth and proliferation, and is active in Ewing sarcoma cells, it seemed plausible that re-expression of an inhibitor of this pathway, SPRY1, could reduce cell proliferation or transformation." (PMID 23527175, 2013). "SPRY1 may be impinging on an alternate growth factor signaling pathway or perform a novel function in the context of a Ewing sarcoma cell." (PMID 23527175, 2013). "We further demonstrate that re-expression of SPRY1, a repressed target of BCL11B, limits the transformation capacity of Ewing sarcoma cells." (PMID 23527175, 2013).
prostatic intraepithelial neoplasia (2 papers, 2014 to 2015). "In conclusion, loss of a single allele of either Spry1 or Spry2 results in the development of prostate intraepithelial neoplasia in mice." (PMID 26075267, 2015). "Recently, it was demonstrated that concomitant prostate-specific deletion of Spry1 and Spry2 in mice resulted in prostatic intraepithelial neoplasia (PIN), while deletion of either Spry 1 or Spry 2 in hemizygous Pten null mice resulted in invasive carcinoma." (PMID 26075267, 2015).
renal agenesis (2 papers, 2010 to 2022). Renal agenesis (RA) is a form of renal tract malformation characterized by the complete absence of development of one or both kidneys (unilateral RA or bilateral RA respectively), accompanied by absent ureter(s). "It was recently reported that the effects of a Ret-Y1062F point mutation, which causes renal agenesis or hypodysplasia similar to that observed in Ret knockout mice, can be rescued by removal of Spry1." (PMID 20084103, 2010). "We found that FGF10, presumably signaling via FGFR2, is an essential component of this alternative signaling, as removing either one or two Fgf10 alleles in a Gdnf−/−;Spry1−/− background caused failure of UB emergence, leading to renal agenesis." (PMID 20084103, 2010). "In contrast, we found that newborn Gdnf−/−;Spry1−/− (abbreviated GGSS) mice displayed only 11% renal agenesis (n = 18) and 89% of kidneys were normally shaped and only slightly smaller than controls (cross-sectional area 70±11% of wild-type)." (PMID 20084103, 2010). "Loss of Gdnf causes renal agenesis because in the presence of SPRY1 the level of FGF10 signaling via FGFR2 is not sufficient to produce the necessary responses, such as an appropriate level of Etv4 and Etv5 expression." (PMID 20084103, 2010). "In contrast to Gdnf or Ret mutations, renal agenesis caused by concomitant lack of the transcription factors ETV4 and ETV5 is not rescued by removing Spry1, consistent with their role downstream of both RET and FGFRs." (PMID 20084103, 2010). "When Spry1 is absent there is no brake on signaling via FGFR2, and GDNF can be removed without causing renal agenesis, due (at least in part) to the effects of FGF10, and to the restoration of Etv4/Etv5 expression; however, UB branching pattern is abnormal." (PMID 20084103, 2010). "We then generated Spry1+/–; Spry2+/– mice either expressing Ret (RetEGFP/+) or not (RetEGFP/EGFP) and analyzed their caudal WDs by EGFP fluorescence at birth, since Ret-knockout animals die shortly after birth owing to renal agenesis." (PMID 36098804, 2022).
anemia (1 paper, 2011). A reduction in the number of red blood cells, the amount of hemoglobin, and/or the volume of packed red blood cells. "The reduced size of Spry1;Tie2-Cre embryos is likely a secondary effect due to defects in hematopoiesis and anemia." (PMID 21483770, 2011).
Arthritis (1 paper, 2025). Inflammation of a joint. "Focusing on the links between skin lesions and arthritis, we utilized these Spry1-cKO mice as a mouse model for PsA and found that SPRY1-deficient keratinocytes produced excessive CXCL10, which bound to CD14 to promote the proinflammatory response of periarticular CD14hi macrophages." (PMID 40471688, 2025). "Moreover, SPRY1 deficiency in the epidermis was sufficient to drive both skin and joint inflammation, suggesting that SPRY1 plays a critical role in skin-joint crosstalk during the development of PsA." (PMID 40471688, 2025).
astrocytoma (1 paper, 2022). "SPRY1 was more expressed in GBM subtypes compared with those in oligodendroglioma and astrocytoma." (PMID 35910677, 2022).
autoimmune disease (1 paper, 2016). A disorder resulting from loss of function or tissue destruction of an organ or multiple organs, arising from humoral or cellular immune responses of the individual to their own tissue constituents. "Other targets of miR-21 are associated with immunity and the pathogenesis of autoimmune diseases such as SPRY1 (Sprouty RTK Signalling Antagonist 1), GNAQ (Guanine Nucleotide-Binding Protein Alpha-Q), PLEKHA1 (Pleckstrin Homology Domain Containing Family A), and CXCR4 (C-X-C Chemokine Receptor 4)." (PMID 27782053, 2016).
Autoimmunity (1 paper, 2012). The occurrence of an immune reaction against the organism's own cells or tissues. "We posit that the ability of Spry1 to mitigate T cell activation may play a role in preventing hyperactive immune responses leading to autoimmunity." (PMID 23166773, 2012).
brain tumor (1 paper, 2019). "We took FREM2 and SPRY1 gene expression, age, sex, and histological type of brain tumor as covariates." (PMID 31357584, 2019).
breast tumor (1 paper, 2016). "By contrast, Spry1 was low in MCF-7 cells, higher in MDA-MB-231 and MDA-MB-157 cells, and Spry2 protein was undetectable in all three MCF-7, MDA-MB-231 and MDA-MB157 breast tumor cell lines." (PMID 26976794, 2016).
chondrodysplasia (1 paper, 2016). "BAR4 is near Spry1, a gene involved in skeletal and muscle development in mice that when overexpressed leads to chondrodysplasia, a skeletal disorder leading to arrested development." (PMID 27019019, 2016).
fibrosarcoma (1 paper, 2025). A malignant mesenchymal fibroblastic neoplasm affecting the soft tissue and bone. "MiR-21 also regulates cell growth via regulating the Sprouty RTK signaling antagonist 1 (SPRY1)/rapidly accelerated fibrosarcoma (RAF)/extracellular signal-regulated kinase (ERK) pathway." (PMID 39941145, 2025).
hydronephrosis (1 paper, 2021). Collection of urine in the renal pelvis that results in dilatation of the renal pelvis and calyces. "However, Spry1 deficient mice on an FVB background survive postnatally with incomplete penetrance of unilateral hydronephrosis in males (~20%) and enlarged uterus in females (~70%)." (PMID 34714716, 2021).
Hydroureter (1 paper, 2010). The distention of the ureter with urine. "However, in the absence of SPRY1, mice lacking GDNF or RET make a normal UB that develops into a normal ureter connected to the bladder, as indicated by the absence of hydroureter." (PMID 20084103, 2010).
interstitial lung disease (1 paper, 2023). A diverse group of lung diseases that affect the lung parenchyma. "Exosomal miR-132-3p from A549 cells accelerated the development of interstitial lung disease through binding to SPRY1, which might serve as an important target for ILDs." (PMID 37454094, 2023).
ischemia (1 paper, 2019). A hypoperfusion of the BLOOD through an organ or tissue caused by a PATHOLOGIC CONSTRICTION or obstruction of its BLOOD VESSELS, or an absence of BLOOD CIRCULATION. "Similar to Spry1 knockdown in cardiomyocytes in vivo, RNAi-mediated Spry1 silencing in isolated cardiomyocytes improved cardiomyocyte survival following simulated ischemia injury." (PMID 30635790, 2019). "In this study, we investigated the role of Spry1 in cardiac ischemia–reperfusion (I/R) injury." (PMID 30635790, 2019).
kidney cancer (1 paper, 2022). Primary or metastatic malignant neoplasm involving the kidney. "It is noteworthy that there was no absolute difference in the protein expression level of NFIA and SPRY1 between normal kidney tissues and kidney cancer." (PMID 36035369, 2022).
liver cancer (1 paper, 2019). An epithelial or non-epithelial malignant neoplasm that arises from the liver. "On the one hand, SPRY1 is considered a candidate tumor-suppressor gene due to its down-regulation in breast, prostate, and liver cancers." (PMID 31357584, 2019).
liver fibrosis (1 paper, 2023). "In liver fibrosis disease, miR-21 had a positive correlation with liver fibrosis, and overexpression of miR-21 promoted collagen production and inflammasome activation when the expression of SPRY1 was inhibited." (PMID 37454094, 2023).
lymph node metastasis (1 paper, 2022). "Besides, high expression of SPRY1 suggested low risk of lymph node metastasis, whereas the high expression of TGFBI suggested high risk of lymph node metastasis." (PMID 36035369, 2022).
lymphoma (1 paper, 2012). A malignant (clonal) proliferation of B- lymphocytes or T- lymphocytes which involves the lymph nodes, bone marrow and/or extranodal sites. "In the lymphoma model we were able to demonstrate that the deletion of Spry1 in T cells led to a more robust response to a whole cell tumor vaccine." (PMID 23166773, 2012).
medullary thyroid carcinoma (1 paper, 2014). "Preclinically, anti-proliferative and tumor suppressing roles have been described for Spry1 in prostate, liver and medullary thyroid cancer cells." (PMID 24932220, 2014).
myocardial ischemia (1 paper, 2019). A disorder of cardiac function caused by insufficient blood flow to the muscle tissue of the heart. "In summary, we found that myocardial ischemia promotes Spry1 protein expression in ischemic cardiomyocytes." (PMID 30635790, 2019). "Further studies are needed to evaluate if inhibition of Spry1 offers novel therapeutic strategy to alleviate cardiac ischemia–reperfusion injury." (PMID 30635790, 2019). "The aim of this study was to investigate the potential role of cardiomyocyte Spry1 in cardiac ischemia–reperfusion (I/R) injury." (PMID 30635790, 2019).
RASopathies (1 paper, 2021). "As expected, RAS proteins are the ones with the highest number of associations, although RASopathies related to SPRED1, MEK1/2, PTPN11, FGFR3 and SPRY1 may regulate RAS signaling differently, affecting primarily the classical RAS versus RRAS signaling." (PMID 34229750, 2021).
rheumatoid arthritis (1 paper, 2025). A chronic, systemic autoimmune disorder characterized by inflammation in the synovial membranes and articular surfaces. "To distinguish the similarity of the Spry1-cKO joint phenotype with PsA from rheumatoid arthritis, we examined C-reactive protein (CRP) and rheumatoid factor levels in Spry1-cKO mice plasma." (PMID 40471688, 2025). "Importantly, the NF-κB signaling pathway, TNF signaling pathway, rheumatoid arthritis, IL-17 signaling pathway, osteoclast differentiation, cytokine-cytokine receptor interaction, and chemokine signaling pathway were highly activated in periarticular CD14hi macrophages of Spry1-cKO mice." (PMID 40471688, 2025).
Sagittal craniosynostosis (1 paper, 2016). A kind of craniosynostosis affecting the sagittal suture. "The SPRY1 mutation (p.Q6fs*8) was de novo in a woman with mild cranial dysmorphism who did not undergo surgery, and was transmitted to both of her children, who both had sagittal craniosynostosis." (PMID 27606499, 2016).
sarcoma (1 paper, 2021). A usually aggressive malignant neoplasm of the soft tissue or bone. "In other types of sarcoma, Spry1 effects are already reported." (PMID 34769378, 2021).